ALDH1A1 (aldehyde dehydrogenase 1 family member A1)
Diseases named in the same sentence as ALDH1A1 in open-access papers (continued):
Sharing a sentence is not in itself a finding about the gene and the disease.
virus infection (2 papers, 2015 to 2017). "We therefore speculated that ALDH1A1 expression was involved in cancer heterogeneity and the differences in prognoses for different virus infection backgrounds and types of cancer." (PMID 28792511, 2017). "All non-tumorous tissues in HCC specimens homogenously expressed ALDH1A1 at low levels, with slightly strong expression in the perivascular area around central vein or portal vein, regardless of the various disease backgrounds such as fibrosis or virus infection." (PMID 26160842, 2015).
alcohol use disorder (1 paper, 2024). "Disulfiram, by inhibiting ALDH1A1 - which was a gene in the alcohol consumption network - is an effective treatment for alcohol use disorder, suggesting that other genes identified by our network could also be viable pharmacological targets." (PMID 38464225, 2024).
angiomyolipoma (1 paper, 2021). A neoplasm with perivascular epithelioid cell differentiation often associated with tuberous sclerosis. "Just as in the TSC2-/- angiomyolipoma cell line S102, in the primary LAM lung tissue derived cell lines the expression of ADH1, ADH4 and ALDH1A1-2-3 showed the same pattern." (PMID 34178631, 2021).
Anxiety (1 paper, 2014). Intense feelings of nervousness, tension, or panic often arise in response to interpersonal stresses. "The ACAG haplotype in block 4 of the ALDH1A1 gene provided evidence of an association with AD (p = 0.03) and weak evidence of an association with AD without symptoms of anxiety (p = 0.06)." (PMID 24567230, 2014). "We investigated whether variation in genes encoding cytochrome P450 2E1 (CYP2E1) or acetaldehyde-metabolising enzymes (ALDH1A1, ALDH2) might alter the risk of AD, with and without symptoms of anxiety, in a Cape population with mixed ancestry." (PMID 24567230, 2014).
Aortic dissection (1 paper, 2025). Aortic dissection refers to a tear in the intimal layer of the aorta causing a separation between the intima and the medial layers of the aorta. "In addition to PGK1 and HMGA1, several other lactylation-related genes identified in our analysis, such as GAPDH and ALDH1A1, may also contribute to the pathophysiological mechanisms of aortic dissection." (PMID 40596702, 2025).
Arthritis (1 paper, 2024). Inflammation of a joint. "In ALDH1A1, the lower the expression, the more likely it was that arthritis was accompanied by fever compared to asymptomatic patients." (PMID 38243323, 2024).
asthma (1 paper, 2022). "Several asthma-related genes were identified: detoxification enzymes (Cyp2a5, Gsto1, Gstp1, Gstm1, and Aldh1a1) were downregulated while Hmgb1 (alarmin) was upregulated." (PMID 35627266, 2022).
behavioural disorders (1 paper, 2023). "There is evidence that ALDH1A1 and ALDH3A1 are important for transparency of the cornea, whereas OXTR has been linked to behavioural disorders and is known to regulate parturition." (PMID 37363400, 2023). "The connection between ALDH1A1 and ALDH3A1 loss and corneal opacities, and OXTR loss and prolonged labour and behavioural disorders provides a new explanation for the extracutaneous features of RXLI." (PMID 37363400, 2023).
bladder (1 paper, 2021). "Moreover, 5637 cell-derived tumorspheres were enriched in active β-catenin and the CSC markers ALDH1A1, Sox-2 and Oct-4, demonstrating that paclitaxel resistance promotes the proliferation of bladder tumorspheres through Wnt/β-catenin pathway." (PMID 35008872, 2021).
chronic nasopharyngitis (1 paper, 2016). "Expression levels of CD44v6 and ALDH1A1 were significantly increased in cancer cells of primary NPC specimens in comparison to chronic nasopharyngitis tissues." (PMID 27647953, 2016). "The present IHC analyses semiquantitatively confirmed that the expression levels of both CD44v6 and ALDH1A1 were increased in NPC tissues in comparison with chronic nasopharyngitis tissues." (PMID 27647953, 2016). "The present study revealed that moderate immunofluorescence staining of ALDH1A1 was observed in chronic nasopharyngitis epithelium." (PMID 27647953, 2016). "Weak immunofluorescence staining of ALDH1A1 and CD44v6 was observed in chronic nasopharyngitis epithelium (a and b)." (PMID 27647953, 2016). "In chronic nasopharyngitis tissues (inflammation), epithelial cells showed weak immunofluorescence staining of ALDH1A1." (PMID 27647953, 2016). "Cancer stem cell markers (CD44v6 and ALDH1A1) were more highly expressed in the biopsy NPC tissues compared with the nasopharyngitis." (PMID 27647953, 2016).
chronic obstructive pulmonary disease (1 paper, 2025). A chronic and progressive lung disorder characterized by the loss of elasticity of the bronchial tree and the air sacs, destruction of the air sacs wall, thickening of the bronchial wall, and mucous accumulation in the bronchial tree. "Conversely, we found that patients with systemic respiratory diseases, including cystic fibrosis and chronic obstructive pulmonary disease (COPD), tended to show downregulation of ALDH1A1 mRNA in ciliated cells." (PMID 40408364, 2025).
coloboma (1 paper, 2014). An abnormality in which a part of a structure in one or both eyes is missing. "Aldh1a3-/- (Raldh3) knockout mice display coloboma, and although Aldh1a1-/- (Raldh1) knockout mice did not have a recognizable ophthalmic phenotype, double knockout Aldh1a1-/-; Alldh1a3-/- mice displayed an even more severe eye phenotype." (PMID 25004007, 2014).
COVID-19 (1 paper, 2023). A disease caused by infection with severe acute respiratory syndrome coronavirus 2. "The protein–protein interaction (PPI) network of DEGs was then constructed and six genes named RAD51, ALDH1A1, UBA52, CUL3, GADD45B, and CDKN1A were identified as the commonly dysregulated hub genes among HFRS and COVID-19." (PMID 37234545, 2023). "Our study uncovered six genes named RAD51, ALDH1A1, UBA52, CUL3, GADD45B, and CDKN1A were found to be commonly dysregulated among HFRS and COVID-19." (PMID 37234545, 2023).
Crohn disease (1 paper, 2014). A gastrointestinal disorder characterized by chronic inflammation involving all layers of the intestinal wall, noncaseating granulomas affecting the intestinal wall and regional lymph nodes, and transmural fibrosis. "Also recently, ALDH1A1 expression in intestinal CD14+ macrophages in tissue from patients with Crohn’s disease was linked to increased RA production and a more inflammatory phenotype." (PMID 25926859, 2014).
dermatitis (1 paper, 2013). An inflammatory process affecting the skin. "In contrast, expression of enzymes responsible for the conversion of retinal to the bioactive vitamin A derivative ATRA (aldehyde dehydrogenases; Aldh1a1, 1a2, and 1a3) was significantly increased only in allergen-induced dermatitis." (PMID 23977003, 2013).
diffuse gastric adenocarcinoma (1 paper, 2016). An adenocarcinoma arising from the stomach. "The ALDH1A1 mRNA level was also decreased in diffuse gastric adenocarcinoma and gastric intestinal type adenocarcinoma, compared with gastric mucosa." (PMID 27015121, 2016). "In Cho's dataset, the transcription levels of ALDH1A1 in both gastric intestinal type adenocarcinoma and diffuse gastric adenocarcinoma were lower than that in gastric tissues (Fold changes were −5.046 and −3.278, respectively)." (PMID 27015121, 2016). "High transcriptional expression of ALDH1A1 was associated with longer OS in gastric intestinal type adenocarcinoma, with HR = 0.6 (0.44–0.83), p = 0.0018, but not in diffuse gastric adenocarcinoma." (PMID 27015121, 2016). "In addition, high transcription activity of ALDH1A1 predicted better OS in gastric intestinal type adenocarcinoma, but not in diffuse gastric adenocarcinoma." (PMID 27015121, 2016).
diffuse large B-cell lymphoma (1 paper, 2023). "In diffuse large B cell lymphoma ARID1A mutations do occur, which might facilitate ALDH1A1 expression." (PMID 37298333, 2023).
ductal carcinoma (1 paper, 2008). "There is no report on RBP4 in the literature in connection with ductal vs. lobular breast cancer distinction while ALDH1A1 protein levels were shown to exhibit differences among the ductal carcinoma patients." (PMID 19116033, 2008).
Dyskinesia (1 paper, 2019). A movement disorder which consists of effects including diminished voluntary movements and the presence of involuntary movements. "Therefore, our findings demonstrate that ALDH1A1–synthesized RA is required for postsynaptic MOR1 expression in the postnatal and adult dorsal striatum, supporting potential therapeutic benefits of RA supplementation in moderating L-DOPA–induced dyskinesia." (PMID 30837649, 2019).
esophageal adenocarcinoma (1 paper, 2020). A malignant tumor with glandular differentiation arising predominantly from Barrett mucosa in the lower third of the esophagus. "In an in vitro model of starvation with depletion of glucose and serum factors in the esophageal adenocarcinoma cell line SKGT-4, the starvation-responsive increase in expression levels of HSP90 (and HSP70) was associated with the expression of CSC markers, such as CD44, ALDH1A1, and ABCG2." (PMID 32268506, 2020).
Fanconi anemia (1 paper, 2014). Fanconi anemia (FA) is a hereditary DNA repair disorder characterized by progressive pancytopenia with bone marrow failure, variable congenital malformations and predisposition to develop hematological or solid tumors. "To identify the molecular network signals that are differentially expressed in ALDH1A1 expressing cells, we initially assessed the expression of Fanconi anemia pathway and tumor resistance to chemotherapeutic agents." (PMID 25216266, 2014).
Fibroadenoma (1 paper, 2020). A benign tumor of the breast characterized by the presence of stromal and epithelial elements. "For fibroadenoma tissues, compared with both fibroadenoma-adjacent and normal tissues, there were six up-regulated (ANXA6, VCP, SERPINH1, galactosidase alpha, NNT, and MMP11) and 38 down-regulated (KRT10, KRT1, ALDH1A1, ECM1, and others) proteins in fibroadenoma." (PMID 33194682, 2020).
gallbladder cancer (1 paper, 2022). "We herein report a case of early-stage gallbladder cancer, BilIN3 (high grade), arising from ADM that was positive for ALDH1A1, an important marker of stem cells and cancer stem cells." (PMID 36359563, 2022).
gastric tumor (1 paper, 2023). "In addition, the levels of CD133 (prominin 1) and ALDH1A1 (aldehyde dehydrogenase 1 family member A1) proteins, which are markers for gastric tumor stem cells, were notably increased in HGC-27-LR cells." (PMID 38012281, 2023).
Gorlin Syndrome (1 paper, 2014). "Our observations suggest that deficiency in the retinoic acid pathway, such as loss of ALDH1A1 expression in GDFs from Gorlin syndrome patients, should be considered when predicting or assessing radiation health effects." (PMID 28250390, 2014). "Further, two different Gorlin syndrome donors characterized by distinct Patched mutations displayed loss of ALDH1A1 protein." (PMID 28250390, 2014). "Results from our proteomics study demonstrated that aldehyde dehydrogenase 1A1 (ALDH1A1) protein expression was deficient in primary dermal fibroblasts from Gorlin syndrome patients (GDFs), as compared with primary normal human dermal fibroblasts (NHDFs) used as controls." (PMID 28250390, 2014). "Therefore, ALDH1A1 deficiency suggests that Gorlin syndrome patients may display retinoic acid-deficiency." (PMID 28250390, 2014).
hypothyroidism (1 paper, 2014). Abnormally low levels of thyroid hormone. "Consequently, compound inactivation of Mct8 and Dio2 leads to a situation more similar to hypothyroidism, but surprisingly some genes profoundly affected in the hypothyroid brain such as Aldh1a1 are not affected by concomitant Mct8 and Dio2 inactivation." (PMID 24618783, 2014).
low grade glioma (1 paper, 2021). A grade I or grade II glioma arising from the central nervous system. "When assessing ALDH1 family proteins in low-grade glioma (LGG), a panel of six LGG samples showed that two samples expressed ALDH1A1 and two samples also expressed ALDH1A2, though to varying degrees." (PMID 34572134, 2021).
meningeal tumours (1 paper, 2013). "Interestingly, ALDH1A1 mRNA expression was higher in the 20 meningeal tumours than in the 32 extra-meningeal tumours (p = 7.5E-4; t-test)." (PMID 24252471, 2013).
mucinous ovarian cancer (1 paper, 2018). An invasive malignant neoplasm that arises from the ovary and is characterized by the presence of malignant epithelial cells that contain intracytoplasmic mucin and may resemble the epithelial cells of the endocervix or gastrointestinal tract. "The immunohistochemical analysis of LOX, COL1A2, COL3A1, COL21A1, and ALDH1A1 was performed for few cases of endometrioid, serous, and mucinous ovarian cancer in order to verify the localization of analyzed proteins in the real cancer tissue." (PMID 30583585, 2018).
ovarian diseases (1 paper, 2024). "Conversely, several downregulated genes crucial for folliculogenesis were also found to be linked to ovarian diseases, namely, genes for sex hormone biosynthesis such as STAR, CYP17A1, and ALDH1A1, along with genes required for follicle development, such as INHA." (PMID 38126810, 2024).
pneumonia (1 paper, 2025). An acute, acute and chronic, or chronic inflammation focally or diffusely affecting the lung parenchyma, caused by an infection in one or both of the lungs (by bacteria, viruses, fungi, or mycoplasma.). "Taken together, these findings suggest that ALDH1A1 deficiency increases pneumonia susceptibility due to the deeper penetration of bacteria into the respiratory tract, rather than affecting resistance immunity." (PMID 40408364, 2025). "Thus, ALDH1A1-deficient mice pre-exposed to PM2.5 exhibited increased susceptibility to pneumonia." (PMID 40408364, 2025).
preeclampsia (1 paper, 2020). Preeclampsia is a hypertensive disorder of pregnancy that is characterized by new-onset hypertension with proteinuria presenting after 20 weeks of gestation, and depending on mild or severe forms may initially present with severe headache, visual disturbances, and hyperreflexia. "A recent study showed that treating decidual MSCs derived from preeclampsia women with an ALDH1A1 activator restored ALDH1A1 activity and improved H2O2-induced oxidative stress resistance in preeclampsia-derived MSCs." (PMID 32711583, 2020).
pterygium (1 paper, 2025). A wedge-shaped fibrovascular lesion arising from the bulbar conjunctiva and extending to the cornea. "Interestingly, corneal epithelial samples of pterygium subjects showed a decreased ALDH1A1 mRNA expression compared to controls (p < 0.0001)." (PMID 40094891, 2025).
renal adenocarcinoma (1 paper, 2023). "In the case of renal adenocarcinoma (769-P), where compounds showed the greatest activity and selectivity, a significant reduction in ALDH1A1 was observed for almost all tested compounds." (PMID 38139832, 2023). "Therefore, it is considered that ALDH1A1 may be an important target for anti-tumor therapies for renal adenocarcinoma." (PMID 38139832, 2023).
respiratory infection (1 paper, 2025). "Considering the vital role of MCC in lower respiratory tract sterility, we next investigated whether ALDH1A1 deficiency affects susceptibility to respiratory infection." (PMID 40408364, 2025).
rosacea (1 paper, 2026). A chronic erythematous skin disorder that affects the face. "Four key genes (ALDH1A1, COL17A1, RELL1, and ZNF404) were identified, with ALDH1A1 as a risk factor and the others as protective factors for rosacea." (PMID 42112773, 2026).
sarcoidosis (1 paper, 2025). Sarcoidosis is a multisystemic disorder of unknown cause characterized by the formation of immune granulomas in involved organs. "However, upregulation of SPP1 was more modest, and unlike NL and NXG macrophages, sarcoidosis lesional macrophages strongly overexpressed APOE, VAT1, TLR8, and ALDH1A1 among other genes." (PMID 39989459, 2025).
Sepsis (1 paper, 2023). Sepsis is defined as life-threatening organ dysfunction caused by a dysregulated host response to infection. "Then, ALDH1A1 was expressed at a low level in sepsis-induced ALI." (PMID 37700323, 2023).
steatosis (1 paper, 2021). Increased lipid within the cytoplasm of cells. "In the comparisons among the normal, steatosis and NASH patients, the expression of ALDH1A1 was significantly higher in the NASH livers than normal livers." (PMID 34096467, 2021).
substance abuse (1 paper, 2024). The use of a drug for a reason other than which it was intended or in a manner or in quantities other than directed. "Drug discovery in cancer research has thus far been applied to ALDH1a1, ALDH1a3, and ALDH3a1 while drug discovery in substance abuse has focused on ALDH2, and discovery in the male contraceptive space has focused on ALDH1a1/a2 or RARα." (PMID 39133222, 2024).
synucleinopathy (1 paper, 2024). A neurodegenerative disease that is characterized by the abnormal accumulation of aggregates of alpha-synuclein protein in neurons, nerve fibers or glial cells. "Given the downregulation of Aldh1a1 that we observe in early synucleinopathy and potential loss of a protective enzyme, DOPAL accumulation and toxicity are mechanisms which could contribute to synucleinopathy progression and should be examined in future studies." (PMID 38172128, 2024). "In our results, Aldh1a1 transcript decreased early in synucleinopathy." (PMID 38172128, 2024).
teratoma (1 paper, 2013). A non-seminomatous germ cell tumor characterized by the presence of various tissues which correspond to the different germinal layers (endoderm, mesoderm, and ectoderm). "Colocalization of SSEA-5 and ALDH1A1 was evident in the teratoma tissue." (PMID 26317026, 2013).
thyroid tumor (1 paper, 2022). A benign or malignant neoplasm affecting the thyroid gland. "Indeed, our Gene Ontology (GO) enrichment analysis revealed a close relationship between ALDH1A1/A3/B1 and ethanol oxidation (GO:0006069), as well as retinol metabolic process (GO:0042572), which are known to be important in detoxification, tumorigenesis, and thyroid tumor progression." (PMID 35280765, 2022).
type 1 diabetes (1 paper, 2018). "In a type 1 diabetes rat model, rats presented lower plasma retinol levels and higher hepatic retinol levels compared to the control rats, as well as lower and higher expression of ALDH1A1 and ALDH1A2, respectively." (PMID 30373117, 2018).